CDC42 (cell division cycle 42)
Diseases named in the same sentence as CDC42 in open-access papers (continued):
Sharing a sentence is not in itself a finding about the gene and the disease.
gastric cancer (continued). "IPA revealed that GINS4 plays key roles in cell proliferation, cell cycle, apoptosis, migration and invasion of gastric cancer by Rac1 and CDC42 and their downstream signaling pathways: MAPK/ERK pathway, PI3K/AKT pathway and PTEN pathway." (PMID 31754397, 2019). "SCIN knockdown inhibited the invasion and metastasis of gastric cancer cells and restrained the filopodium formation and Cdc42 expression." (PMID 31736743, 2019). "In all, these findings demonstrated to the best of our knowledge, the up‐regulation of MICAL‐L2 in gastric cancer cells is attributed to EGFR stability in a Cdc42‐dependent manner." (PMID 31034158, 2019). "Collectively, a novel circMLLT10/miR-509-3-5p/GINS4/Rac1/CDC42 axis was established in gastric cancer growth and progression." (PMID 31754397, 2019). "For instance, miR-133 is an important negative regulator of Cdc42/P21-activated kinases (PAK pathway) in gastric cancer by silencing Cdc42 expression, which is closely correlated with the tumor size, invasion depth and adjacent organ metastasis." (PMID 30174600, 2018). "Since hsa-miR-29c-5p and hsa-miR-133 are down-regulated in gastric cancer and have the same target gene (CDC42), it’s possible to observe that independent mechanisms are altered in a similar way to maintain the malignant state of the cell." (PMID 30376837, 2018). "Our study showed that the exogenous expression of hsa-miR-29c-5p is also able to regulate the expression of CDC42 in intestinal type gastric cancer cell lines, suggesting that this miRNA is another fundamental element in the regulation of this gene." (PMID 30376837, 2018). "Expectedly, NKX6.3 significantly decreased the protein expression of RhoA, Cdc42, p-Rac1/Cdc42, and Rac1/2/3 in gastric cancer cells." (PMID 27333045, 2016). "It was previously indicated that the overexpression of miR-137 can induce cell cycle G1 arrest in gastric cancer cells through targeting Cdc42." (PMID 27764771, 2016). "In conclusion, the expression of ST3GAL4 leads to SLex antigen expression in gastric cancer cells which in turn induces an increased invasive phenotype through the activation of c-Met, in association with Src, FAK and Cdc42, Rac1 and RhoA GTPases activation." (PMID 23799130, 2013). "Moreover, they discovered that AFAP1L1 induction facilitated epithelial-mesenchymal transition (EMT) to promote the advancement of gastric cancer by activating CDC42 and ITGA5 signaling pathways, with mediation from VAV2." (PMID 37737201, 2023). "Such alterations in morphology, in addition to the prompt adhesion of gastric cancer cells, may be due to complete circumferential cell adhesion to the plate, which was augmented through Cdc42 in the presence of the Ln511-E8 fragment." (PMID 35723363, 2022). "When we analyzed the role of Cdc42 in the maintenance of E-cadherin stability in gastric cancer cells, we observed that a constitutively active form of Cdc42 significantly abrogated the upregulation of E-cadherin expression and the downregulation of cell migratory potential in MICAL2-depleted cells." (PMID 36064550, 2022). "MiR-148b-3p represses gastric cancer cell metastasis by targeting the Dock6/Rac1/cdc42 axis." (PMID 35549631, 2022). "Therefore, we reasoned that 14-5-18 treatment would lead to a reduction of the level of active Rac1 and Cdc42 in gastric cancer cells." (PMID 36418900, 2022). "As MICAL family members have a similar structure, we hypothesized that MICAL2 might promote YAP nuclear translocation via ROS generation and/or Cdc42 activation, thereby promoting gastric cancer cell proliferation." (PMID 34650666, 2021). "Furthermore, MICAL2 facilitates gastric cancer cell migration by promoting MRTF-A-dependent activation of cell division control protein 42 homolog (CDC42) and expression of MMP9." (PMID 33842533, 2021). "Silencing of CDC42 markedly inhibits the migration and invasion of gastric cancer cells." (PMID 33842533, 2021).
gastric cancer (continued). "FARP1 promoted cell motility through activating CDC42 in gastric cancer." (PMID 34252883, 2021). "Although Cdc42 is known to exert its function by switching between an inactive GDP-bound state and an active GTP-bound form, the mechanisms involved in activating Cdc42 in gastric cancer cells are largely unknown." (PMID 34650666, 2021). "Thus, it appears reasonable to conclude that FARP1 activates CDC42 and facilitates the abilities of cell migration and invasion by promoting the formation of filopodia and invadopodia in gastric cancer." (PMID 32029704, 2020). "Rac1 and CDC42 expression were detected by IHC with the TMA of gastric cancer tissues." (PMID 31754397, 2019). "In gastric cancer, miR-29a inhibits Cdc42 expression at both the protein and RNA levels." (PMID 31662747, 2019). "Furthermore, SCIN promoted the invasion and metastasis of gastric cancer cells through activating the Cdc42 pathway to increase the formation of filopodia." (PMID 31736743, 2019). "Accordingly, ITGA2 signaling inhibition may prevent metastasis of gastric cancer through down-regulating Rac 1/CDC42 signaling pathway." (PMID 29743821, 2018). "Next, we determined the expression of NKX6.3, E-cadherin, N-cadherin, β-catenin, p-GSK3βY216, CLND1, RhoA, Cdc42, Rac1/2/3, Snail, Slug and Vimentin proteins in 7 gastric cancer tissues at different TNM stages and compared with expression in non-tumorous gastric mucosal tissues." (PMID 27333045, 2016). "Moreover, adhesion of the gastric cancer cells to Ln511-E8 fragment-coated plates was reduced by the Cdc42 GTPase inhibitor in a dose-dependent manner, suggesting the involvement of Cdc42 in the Ln511-E8 fragment-induced enhanced adhesion of gastric cancer cells." (PMID 35723363, 2022). "However, based on our results, Cdc42 may be involved in the Ln511-E8 fragment-induced enhanced adhesion of gastric cancer cells." (PMID 35723363, 2022). "Additionally, downregulation of CDC42 could exert crucial effects on migration and invasion of gastric cancer cells." (PMID 35399723, 2022). "To determine whether NKX6.3 reduces gastric cancer cell migration through down-regulation of the Rho-GTPase family, we examined the expression of CD2-associated protein (CD2AP), RhoA, Cdc42, p-Rac1/Cdc42 and Rac1/2/3 proteins, in AGSNKX6.3 and MKN1NKX6.3 cells." (PMID 27333045, 2016). "Research indicates that the atypical Rho GEF DOCK6 facilitates the proliferation, migration, and invasion of gastric cancer cells while also enhancing chemo- and radio-resistance via the DOCK6/Rac1/Cdc42 axis and the DOCK6/WNT/β-catenin signaling pathway." (PMID 41188920, 2025). "There were different pathways, for example, in gastric cancer, via directly combination with Rac1/CDC42, GINS4 activated Rac1/CDC42 and then influence the downstream pathways." (PMID 35896011, 2022). "There is evidence that hsa‐miR‐29c‐5p is an important regulator of CDC42 and DNMT3A genes in the pathogenesis of gastric cancer." (PMID 35585716, 2022). "Ectopic expression of MICAL2 augmented MRTF-A levels in the nucleus, and promoted the activation of CDC42, MMP9 expression, and gastric cancer cell migration." (PMID 33842533, 2021). "We found that ectopic expression of MICAL2 in gastric cancer cells increased MRTF-A accumulation in the nucleus, which was accompanied by enhanced MMP9 transcription and CDC42 activation." (PMID 33842533, 2021). "Particularly, our previous study indicated that circMLLT10 served as a sponge of miR-509-3-5p, and promoted gastric cancer cell progression through increasing the expression of GINS4 and then activating Rac1 and CDC42." (PMID 34656159, 2021). "In gastric cancer cells, FARP1 knockdown decreased cell motility, whereas FARP1 overexpression promoted cell motility and filopodium formation via CDC42 activation." (PMID 32029704, 2020).
gastric cancer (continued). "Our findings indicate that ASTX can suppress H. pylori-induced gastric cancer progression by inhibiting cytoskeleton reorganization and reducing cell motility through downregulation of c-MET, EGFR, PI3KC2, PLCγ1, Cdc42, and ROCK1." (PMID 32679742, 2020). "In conclusion, ASTX can suppress H. pylori-induced gastric cancer progression by inhibiting cytoskeleton reorganization and reducing cell motility through downregulation of c-MET, EGFR, PI3KC2, PLCγ1, Cdc42, and ROCK1." (PMID 32679742, 2020). "We also discussed the down-regulation of N-WASP, PAK and LIMK, downstream of Cdc42 and Rac1, which altered actin organization and was involved in targeting ITGA2 inhibited cell migration of gastric cancer cells." (PMID 29743821, 2018). "Up-regulation of CDC42 and DNMT3A genes and down-regulation of APC gene in gastric cancer have several implications in the malignancy of the cell." (PMID 30376837, 2018). "Our previous work showed that some Rho GTPases, including Rho, Rac1 and Cdc42, play critical roles in gastric cancer (GC); however, how they are regulated in GC remains largely unknown." (PMID 29587866, 2018). "Current studies indicate that both Rac1 and Cdc42 regulate hypoxia inducible factor (HIF)-induced VEGF expression in response to hypoxia in human hepatocellular carcinoma and gastric cancer cell lines." (PMID 20067638, 2010). "When we analysed the role of Cdc42 on EGFR stability in gastric cancer cells, we observed that the silencing of Cdc42 impaired MICAL‐L2‐induced EGFR up‐regulation and active form of Cdc42 significantly rescued the attenuated EGFR expression in MICAL‐L2‐depletion cells." (PMID 31034158, 2019). "Alternatively, ongoing studies in our laboratory have revealed that Rac1, but not RhoA or Cdc42, is activated in RhoGDI2-overexpressing gastric cancer cells." (PMID 24185104, 2013). "As Cdc42 GTPase inhibitors are a selective, reversible, non-competitive inhibitor of Cdc42 GTPases, these results indicate the possible involvement of Cdc42 in the Ln511-E8 fragment-induced enhanced adhesion of gastric cancer cells, whereas Rac1 and Rho are not or only partially involved." (PMID 35723363, 2022). "Our results also showed that hsa-miR-29c-5p is an important regulator of CDC42 and DNMT3A genes in the intestinal subtype gastric cancer and hsa-miR-135b-5p regulates the APC gene in both intestinal and diffuse subtypes of GC." (PMID 30376837, 2018). "However, it is not clear that miR-137 functions in gastric cancer by targeting Cdc42." (PMID 29596304, 2018). "Similar to others findings, here we found that hypoxia elevated both Rac1-GTP and Cdc42-GTP levels, but not RhoA-GTP in gastric cancer cells." (PMID 31019460, 2019). "Furthermore, we found that NKX6.3 functions as a negative transcriptional regulator of RhoA, Cdc42, Rac1, Rac2, Skp2 and c-Myc genes and completely inhibits c-Myc-p300/CBP-Skp2-Miz1 and Max complex formation, thereby preventing gastric cancer cell migration and invasion." (PMID 27333045, 2016).
glioma (57 papers, 2011 to 2025). A benign or malignant brain and spinal cord tumor that arises from glial cells (astrocytes, oligodendrocytes, ependymal cells). "As a key member of the Rho-GTPase protein family, aberrant activation or upregulation of Cdc42 has been associated with the malignant progression of glioma through PI3K/AKT signaling." (PMID 40533501, 2025). "To further investigate the association between immune cells in glioma and CDC42 expression, we computed the infiltration ratio of 22 types of TIICs in the 2 groups of CDC42 high and low expression using the CIBERSORT algorithm." (PMID 37476838, 2023). "We then investigated the association between CDC42 expression levels and several clinicopathological features of glioma in a total of 1,257 glioma patients from the TCGA and CGGA databases, respectively." (PMID 37476838, 2023). "Mechanistically, TRIM56 was found to interact with IQGAP1 to promote its K63-linked ubiquitination and inhibit degradative K48-linked ubiquitination at Lys-1230, thus promoting CDC42 activation in glioma cells." (PMID 36870986, 2023). "To compare the effects of miR-10b and U6 perturbations, we utilized CDC42, one of the critical genes implicated in glioma biology, whose splicing is modulated by miR-10b." (PMID 35033060, 2022). "Quantitative, real-time PCR and western blot were used to detect PI3K/ATK and CDC42 signals associated proteins expression in glioma." (PMID 33408794, 2021). "Integrins have recently been implicated in promoting the motility of glioma cells via activation of multiple small GTPases including Rac1 and Cdc42." (PMID 26377974, 2015). "CD44/CD155-silencing significantly inhibited the invasive phenotype of glioma cells associated with decreased expression of some of the key mediators of invasion, particularly F-actin, integrins, Rac 1/2/3, RhoA and Cdc42." (PMID 22363471, 2012). "In conclusion, the prognoses of glioma patients are influenced by CDC42, which is associated with immune infiltration, and CDC42 could be an immunotherapy target for glioma." (PMID 37476838, 2023). "NSUN4-mediated high m5C levels promoted ALYREF binding to CDC42 mRNA and regulated its stability, thereby promoting glioma malignant progression." (PMID 41462962, 2025). "It has been proved that SLIT2/ROBO1 signaling inhibits glioma cell migration and invasion by inactivation of Cdc42-GTP." (PMID 38279111, 2024). "The 3D spheroid-based invasion assays of glioma stem cells also revealed that knockdown of CDC42 or treatment with the CDC42 specific inhibitor ZCL278 inhibited the invasion-promoting effect of TRIM56 in glioma cells." (PMID 36870986, 2023). "We discovered that dangerous pathological classifications of gliomas, such as glioblastoma, had high levels of CDC42 expression." (PMID 37476838, 2023). "In a nutshell, lncRNA SNHG15 promoted the growth of glioma microvascular endothelial cells primarily by positively regulating the miR-451/VEGFA/Cdc42 axis, thereby pointing to possible diagnostics and therapeutics based on the axis." (PMID 37056344, 2023). "Our study identified TRIM56 as a glioma-favoring factor that promotes the motility of glioma cells in vitro and in vivo by potentiating CDC42 activation in an IQGAP1-dependent manner." (PMID 36870986, 2023). "Functional enrichment analysis showed that CDC42 was highly correlated with immune and inflammatory responses in glioma." (PMID 37476838, 2023). "For instance, both algorithms showed a considerable enrichment of Treg cells in samples of glioma with high CDC42 expression." (PMID 37476838, 2023). "High expression of CDC42 in glioma patients was positively correlated with poor prognostic factors (higher WHO grade, IDH wild-type, MGMT non-methylated status, and 1p19q non-codeletion status)." (PMID 37476838, 2023). "Taken together, these results demonstrated that the positive effect of TRIM56 on glioma cell motility is mediated via CDC42 activation." (PMID 36870986, 2023).
glioma (continued). "Functional enrichment analysis revealed that the enrichment of CDC42 was connected to several processes that encouraged the development of gliomas, including some immune and inflammatory responses." (PMID 37476838, 2023). "Mechanistically, SNHG15 elevated VEGFA and Cdc42 expression by sponging miR-451 at the post‐transcriptional level, facilitating the angiogenesis of glioma." (PMID 37056344, 2023). "Cell motility in glioma cells is associated with Rho-family GTPases, including RhoA, Ras-related C3 botulinum toxin substrate (RAC), and cell division control protein 42 homolog (CDC42), which regulate the actin cytoskeleton." (PMID 38264122, 2023). "We found that CDC42 was highly enriched in high-grade glioma patients, IDH wild-type glioma patients, non-methylated glioma patients, and non-codeletion glioma patients in TCGA and CGGA databases." (PMID 37476838, 2023). "Although the relationship between CDC42 and a variety of cancers in multiple databases was integrated, and the expression characteristics of CDC42 in glioma were also analyzed, the study still has certain limitations." (PMID 37476838, 2023). "The multivariate Cox analysis pointed out that CDC42 was a poor independent prognostic factor for glioma patients." (PMID 37476838, 2023). "Subsequently, CDC42 expression levels in various clinical and molecular biological characteristics of glioma were explored through TCGA and CGGA databases." (PMID 37476838, 2023). "The heat map indicated that CD8+ T cells, Treg cells, T helper (Th) cells, and macrophages were significantly infiltrated in CDC42 hyper-expression glioma samples, yet natural killer (NK) cells showed the opposite result." (PMID 37476838, 2023). "Our study found that several immune checkpoints (BTLA, CD200R1, PD-L1, B7-H3, CD70, CTLA4, IDO1, and PD1) in patients with CDC42 high expression glioma were upregulated compared to the CDC42 low expression group." (PMID 37476838, 2023). "This is believed to be the primary mechanism through which TRIM56 activates CDC42 to enhance glioma cell migration and invasion." (PMID 36870986, 2023). "The KM curves demonstrated that the survival time of glioma patients in the CDC42 high expression group was shorter than the CDC42 low expression group." (PMID 37476838, 2023). "In human gliomas, Cdc42 is frequently overexpressed and Cdc42 expression correlates with higher glioma grade and poor prognosis for the overall survival of glioma patients." (PMID 33960104, 2022). "We crucially identified that KIF4A drives gliomas growth by transcriptional repression of Rac1/Cdc42 to induce cytoskeletal remodeling in glioma cells." (PMID 36606197, 2022). "It is likely that a functional JAK3‐STAT3‐IQGAP1‐mediated Cdc42 activation pathway exists in human glioma cells." (PMID 33960104, 2022). "On the other hand, miR-153 declines the expression of angiogenesis promoting factors such as VEGFA and cdc42 by binding to 3 ́UTR of their mRNAs in glioma." (PMID 36158686, 2022). "It has been reported that angiogenic activity of LncRNA SNHG15 is regulated by suppressing miR-153, which targets VEGFA and cdc42 in glioma." (PMID 36158686, 2022). "The receptor proteins tyrosine phosphatase and dynamin 2 also participate in the metastasis of glioma cells and activate Rac1 and Cdc42." (PMID 35154449, 2022). "Elevated expression of Cdc42 has been linked to increased GBM progression with high‐tissue invasiveness, shorter progression‐free survival in mice, and poor prognosis of glioma patients." (PMID 33960104, 2022). "We, therefore, concluded that miR-10b exerts its glioma-promoting activity, in part, by binding U6 snRNA and thereby affecting CDC42 splicing." (PMID 35033060, 2022). "Treatment of three different patient‐derived GBM cell models (GBM10, GBM34, GBM146) and the glioma cell line U87MG with human recombinant CTRP8 consistently resulted in a 40–50% upregulation of Cdc42 protein." (PMID 33960104, 2022).